CRP (C-reactive protein)
Diseases named in the same sentence as CRP in open-access papers (continued):
Sharing a sentence is not in itself a finding about the gene and the disease.
sacroiliitis (continued). "It is unclear if platelet count is a meaningful predictor, since other inflammatory markers (WBC, ESR, and CRP) were not predictive of sacroiliitis." (PMID 25067925, 2014). "Comparisons revealed significant statistical differences in the patient group with sacroiliitis and the group without sacroiliitis, in terms of some of the parameters (age, inflammatory back pain, enthesitis, and CRP level)." (PMID 24899899, 2014). "Comparison between patients with and without sacroiliitis revealed statistically significant differences in terms of some of the parameters (age, inflammatory back pain, enthesitis, and CRP levels)." (PMID 24899899, 2014). "There is no specific blood test which points to the diagnosis of pyogenic sacroiliitis; white blood cells count may be increased or normal; ESR and CRP may be elevated in the majority of cases, but while they are sensitive, they may not be specific." (PMID 22829838, 2012). "In our study, of the 55 patients with AAU and negative sacroiliitis who were examined after two years, two patients were diagnosed as axSpA based on newly occurring inflammatory back pain, active sacroiliitis defined by MRI and abnormal CRP." (PMID 35054328, 2022). "In addition, in patients with early-phase axSpA, HLA-B27 is associated with more prominent inflammation on SIJ MRI, whereas common serum inflammatory biomarkers, such as C-reactive protein (CRP) and erythrocyte sedimentation rate (ESR), are incapable of predicting early sacroiliitis." (PMID 34243762, 2021). "In this 52-Week, placebo-controlled study in nr-axSpA patients with elevated CRP and/or active sacroiliitis on MRI at baseline, MRI sacroiliitis and HLA-B27 positivity, but not elevated CRP or responses at Week 12, were predictive of long-term clinical response to CZP." (PMID 34715908, 2021). "According to the ASAS-EULAR treatment guideline, either an elevated CRP or positive MRI may be taken into consideration for bDMARD therapy in patients with axSpA, irrespective of the presence or absence of radiographic sacroiliitis." (PMID 34481517, 2021). "However, this locus was neither associated with other inflammatory parameters (ASDAS CRP, BASDAI, CRP of MRI spinal inflammation assessed by Berlin score) nor radiographic sacroiliitis." (PMID 30646942, 2019). "However, compared with C-axSpAnd, patients were not selected for elevated MRI and/or CRP; eligible patients were required to have inflammatory back pain, with approximately 30% presenting with radiographic sacroiliitis meeting mNY classification criteria at baseline." (PMID 34715908, 2021). "Hence, patients with fever had higher values of inflammatory indicators (ESR, CRP level, platelet count), more sacroiliitis, and more enthesitis than those without fever, which may be not beneficial for disease control." (PMID 26030261, 2015). "It is crucial to consider objective indicators of inflammatory activity, such as MRI findings or elevated C-reactive protein (CRP) levels, when initiating biological treatments for patients with axSpA lacking radiographic sacroiliitis." (PMID 38803407, 2024). "AAU patients with sacroiliitis had significantly higher disease activity compared to patients without sacroiliitis (ASDAS: 1.46 (0.93–2.05) vs. 0.9 (0.64–1.53) respectively, p = 0.006; CRP: 4.43 (1.76–10.44) vs. 1.22 (0.65–2.92) respectively, p < 0.0001)." (PMID 35054328, 2022). "However, the baseline MRI sacroiliitis score and CRP could not predict the achievement of an ASAS20 response at week 24 after 6 infliximab infusions, although they were considered as predictors of clinical response at week 12 after 3 infliximab infusions in our study." (PMID 26273654, 2015). "The current study investigated whether there were differences in ESR, CRP, and some biomarkers (MMP3, IL-17, IL-22, IL-23) in relation to clinical indices of disease activity and the presence/absence of sacroiliitis signs on X-rays and MRIs in an Italian cohort with early and confirmed axSpA." (PMID 31440510, 2019).
steatosis (70 papers, 2009 to 2026). Increased lipid within the cytoplasm of cells. "Multivariate linear regression analysis revealed that LBP was associated with steatosis score and circulating C-reactive protein, aspartate aminotransferase, and fibrinogen levels." (PMID 28216979, 2017). "In another study, a positive association between the degree of steatosis and hs-CRP was observed (P < 0.05) after adjusting for BMI." (PMID 27891128, 2016). "Steatosis score at sonography was well associated with spleen volume (rho = 0.40, P = 0.01) and C-reactive protein levels (rho = 0.49, P = 0.002)." (PMID 19291292, 2009). "The association between CRP and steatosis is likely to be complex, and factors other than weight status might also contribute." (PMID 33919641, 2021). "The ROC curve, a cutoff of hs-CRP = 7 mg/L, showed a reasonable specificity (76%) for detecting biopsy-proven fibrosis and steatosis." (PMID 37029427, 2023). "USS steatosis and elevated ALT were positively associated with insulin, and elevated ALT and AST positively associated with CRP, although these were imprecisely estimated with wide CIs." (PMID 30687796, 2018). "In contrast to our study, USS steatosis in that adult cohort was also associated with small HDL particle concentration, CRP, glucose, lactate and pyruvate, and the magnitudes of associations with amino acids were stronger than we found." (PMID 30687796, 2018). "Multivariate linear regression analysis revealed that steatosis score (P = 0.0033), circulating CRP (P = 0.0032), AST (P = 0.0151), and FIBG (P = 0.0181) were independent predictors of LBP." (PMID 28216979, 2017). "Treatment decreased serum ALT (p < 0.0001) and hs-CRP (p < 0.005) and improved steatosis (6/10), necroinflammation (8/10), fibrosis (4/10)." (PMID 25533004, 2014). "Nine had H-HCA (25%) characterized by steatosis and loss of L-FABP expression; 20 had IHCA (55.5%) showing CRP and/or SAA expression, sinusoidal dilatation, and variable inflammation; and 1 patient had both H-HCA and IHCA." (PMID 23533787, 2013). "For example, high-sensitivity CRP (hs-CRP) levels were significantly higher in patients with NASH compared with those with steatosis in a Japanese study." (PMID 24252302, 2013). "The primary endpoints were measurements in SVR, liver enzyme, cholesterol, triglyceride, CRP, glucose, and insulin levels; and Homa-IR, fibrosis, and steatosis scores." (PMID 22087124, 2011). "Since both steatohepatitis and steatosis group was obese in our study, similarly elevated CRP probably was related to adiposity." (PMID 19222849, 2009). "Serum CRP levels were significantly increased in patients with steatohepatitis and steatosis compared to controls." (PMID 19222849, 2009). "However, CRP mRNA expression in the liver is significantly elevated in NASH patients compared to patients with simple steatosis, thus, suggesting a pathogenetic implication of this protein in steatohepatitis." (PMID 37029427, 2023). "In addition, steatohepatitis patients had significantly higher sCD163, HbA1c, triglycerides and CRP compared to patients with simple steatosis, while amylase, HDL and LDL were lower." (PMID 35566397, 2022). "According to serological parameters, patients with steatosis presented a higher level of fasting plasma glucose (p = 0.024), ferritin (p = 0.047), CRP (p = 0.048), total cholesterol (p = 0.031), LDL-c (p = 0.009), and serum uric acid (p < 0.001), and a low level of HDL-c (p = 0.006)." (PMID 33925569, 2021). "Indeed, low BMD is significantly associated with NASH presenting elevated alanine aminotransferase (ALT) and C-reactive protein (CRP) than in simple steatosis." (PMID 33807573, 2021). "The hepatocellular damage is indicated by elevated serum aminotransferase levels, and the increase in the C-reactive protein (CRP) could be used as a marker of inflammation and steatosis." (PMID 29887885, 2018). "The AUROC for distinguishing between NASH and steatosis using hs-CRP was 0.833." (PMID 24252302, 2013).
steatosis (continued). "CRP levels are known to correlate significantly with NAFLD histological features (degree of steatosis, necro-inflammation and fibrosis); giving support to the earlier hypothesis that NAFLD is associated with low-grade systemic inflammation." (PMID 23554890, 2013). "Although we did not measure the serum level of inflammatory cytokines, this might explain the equally elevated serum CRP levels in both steatohepatitis and steatosis groups in our study." (PMID 19222849, 2009). "A notable statistical association was found between significant fibrosis and other factors, including higher BMI, waist circumference, FBS, HbA1C, HOMA-IR, Hs-CRP, Triglyceride, ALT, AST, alkaline phosphatase, Uric Acid, NFS, and degree of steatosis." (PMID 40531393, 2025). "C‐reactive protein is directly related to NAFLD because CRP is produced by the liver and adipose tissue, and this biomarker is significantly higher in NASH compared to simple steatosis." (PMID 40951584, 2025). "Hs-CRP levels had positive correlation with NASH and steatosis at histology (p value = 0.042, p value = 0.011, respectively)." (PMID 37029427, 2023). "Of note, some H-HCA can be devoid of steatosis and some IHCA can show very little inflammation or show steatosis, which makes both immunostains (LFABP and CRP) useful for the right diagnosis in such cases." (PMID 35954333, 2022). "The first cluster displayed relatively higher values of hematocrit, CRP, LDL-c, direct bilirubin, glucose, creatinine, and AST in those with ultrasonographic diagnosis of moderate or severe steatosis." (PMID 32498337, 2020). "Probiotic supplementation and lifestyle modification, when compared to lifestyle modification alone, significantly reduced TNF-α, CRP (C reactive protein), AST, HOMA-IR, serum endotoxin, steatosis and the NASH activity index." (PMID 30901929, 2019). "AST, ALT, γGT, CRP, TNF-α and IL-6 as well as the histological characteristics (steatosis and fibrosis of the patients) were significantly improved compared with the patients who received the placebo." (PMID 28820468, 2017). "Levels of C-reactive protein (CRP), a peptide involved in the inflammatory response, has a direct relationship to the degree of steatosis in obese patients, indicating its usefulness as a biomarker." (PMID 29177105, 2017). "B. longum with FOS reduces TNF-α, CRP, serum AST levels, HOMA-IR, serum endotoxin, steatosis, and the non-alcoholic steatohepatitis activity index significantly." (PMID 29276488, 2017). "Experimental group: decrease in TNF-α, CRP, AST, HOMA-IR, endotoxin levels; steatosis; NASH activity index." (PMID 25479248, 2014). "Patients with grade 2 + 3 steatosis had significantly higher CRP levels than grade 1 or non-NAFLD patients." (PMID 39842820, 2025). "Also, it was demonstrated that B. longum accompanied with FOS decreases C- reactive protein (CRP), TNF-α, serum Aspartate transaminase (AST) levels, serum endotoxin, steatosis, HOMA-IR, and the nonalcoholic steatohepatitis activity index significantly." (PMID 35204750, 2022). "The observed pre-intervention indices changes, such as the decreased liver fibrosis and steatosis degrees, and changes in the levels of TC, LDL, ALT, AST, as well as in CRP-hs and NTproBNP cardiac overload indicator were significantly more pronounced (p = 0.02 − 0.001) in the IHHE group." (PMID 35327372, 2022). "CRP can be used as an additional marker for diagnosis of NAFLD but it has no value in discrimination of steatohepatitis from simple steatosis." (PMID 19222849, 2009). "Moreover, NLR emerged as a more efficient biomarker in the prediction of NASH and liver fibrosis than C reactive protein (CRP), and was independently correlated with histological changes which are typical of NAFLD, such as ballooning degeneration, lobular inflammation, steatosis and fibrosis degree." (PMID 38239291, 2023). "They found NLR to increase significantly with steatosis and fibrosis, whereas CRP did not." (PMID 37601979, 2022).
steatosis (continued). "Moreover, metabolic abnormalities including an increased value of fasting glucose, ferritin, CRP, serum uric acid, total cholesterol, LDL-c, triglycerides, and a low level of HDL-c were more frequent in patients with steatosis compared with those with a CAP score <237 dB/m." (PMID 33925569, 2021).
Arrhythmia (69 papers, 2005 to 2025). Any cardiac rhythm other than the normal sinus rhythm. "Cytokines like IL-6, TNF-α, and CRP disrupt cardiac function, increase oxidative stress, and promote fibrosis, heightening arrhythmia risk." (PMID 40281050, 2025). "Several studies have shown that higher baseline CRP levels after electrical cardioversion are associated with an increased risk of arrhythmia recurrence." (PMID 40507635, 2025). "Following multivariate analysis, cancer, arrhythmias, and high C-reactive protein levels were found to be factors independently associated with death." (PMID 37685758, 2023). "Our findings corroborate previous studies and confirm that CRP is a key indicator of arrhythmia risk." (PMID 36855116, 2023). "Past studies suggested possible relationship between increased CRP level, complement activation and the increased risk of post-surgery arrhythmia." (PMID 33407078, 2021). "In our study, only two dogs had elevated concentrations of CRP at admission, which made statistical analysis to investigate potential associations with cTnI and the presence of arrhythmias impossible." (PMID 28468664, 2017). "Various inflammatory mediators, such as C-reactive protein (CRP), IL-6 and platelet-activating factor, have been associated with arrhythmias through the modulation of ion channel function." (PMID 25893644, 2015). "In the present study, our results suggest that lower CRP levels, together with lower Neu and LKc counts 24 h after ablation, are associated with a significantly higher degree of late arrhythmia recurrence, which was also particularly common in patients with lower TGF-β1 levels before and after PVI." (PMID 40507635, 2025). "Combined with the results of the ROC curve analysis, the diagnostic criteria for CRP can be further refined, for example: When the CRP level is 8.49–10.19 mg/L, the risk of patients with arrhythmias is reduced; when the CRP level is >10.19 mg/L, the risk of poor prognosis is increased." (PMID 37575983, 2023). "Furthermore, lower values of glomerular filtration rate and hemoglobin, higher circulating levels of troponin, C-reactive protein, and procalcitonin, and higher values of QTc dispersion were found to be associated with the risk of arrhythmia." (PMID 36158797, 2022). "The significant association of CRP concentration with symptoms suggests that inflammation might play a role in the pathophysiology of arrhythmias in BrS." (PMID 22203916, 2011). "Although ghrelin therapy resulted in a shorter duration of SIRS, a lower postoperative level of CRP, and a decrease in the total percentage of bodyweight loss, it did not affect the risk of morbidity outcomes such as pulmonary complications, wound complications, anastomotic leak, or arrhythmia." (PMID 37314533, 2023). "Children with MIS-C often present severe gastrointestinal and neurological symptoms, higher frequency of shock, arrhythmias, and ventricular dysfunction, lower platelet and lymphocytes counts, and higher C-reactive protein (CRP) levels than classic KD." (PMID 41135595, 2025). "Comparison between inflammatory markers (IL-6, CRP, and procalcitonin) and arrhythmia incidence showed that inflammatory markers were significantly higher in patients with arrhythmia (IL-6: p=0.013, CRP: p=0.025, procalcitonin: p=0.001)." (PMID 39434929, 2024). "The levels of CRP and several composite inflammatory indicators, such as SII, NLR, PLR, and LMR, were more closely associated with arrhythmia risk than single-cell count markers such as lymphocyte, neutrophil, and monocyte." (PMID 36855116, 2023). "In this multi-ethnic study cohort, we found that RANTES is associated with sex, EMMPRIN is associated with a history of arrhythmia and LDL levels, MMP-2 with age, and MMP-9 with ethnicity and hs-CRP levels." (PMID 36555898, 2022).